MIR4470 (microRNA 4470)
Synonyms: hsa-mir-4470; mir-4470
Gene: MicroRNA gene on chromosome 8 (61,714,788 to 61,714,859, forward strand). Ensembl gene ENSG00000264408.
Homologues: Orthologues: chimpanzee MIR4470 (100% identical).